NNMT (nicotinamide N-methyltransferase)
Diseases named in the same sentence as NNMT in open-access papers (continued):
Sharing a sentence is not in itself a finding about the gene and the disease.
cancer (continued). "Nicotinamide N-methyltransferase (NNMT) is an S-adenosyl-l-methionine (SAM)-dependent cytosolic enzyme, and a growing body of evidence suggest that it plays an essential role in cancer progression." (PMID 40853419, 2025). "Nicotinamide N-methyltransferase (NNMT), a cytoplasmic protein, is involved in the progression and spread of a variety of cancer types." (PMID 39295619, 2024). "In this study, we uncovered the oncogenic role of NNMT in ESCC lymph node metastasis by promoting nicotinate and nicotinamide metabolism and exerting broad influence to epigenetic landscape of cancer cells." (PMID 38291241, 2024). "In cancer, the HMTs that methylate the H3K9 residue showed a stronger relationship to NNMT, while the relationship to methyltransferases targeting other residues was weaker, albeit still highly significant." (PMID 37883365, 2023). "Since our findings validated the prognostic role of NNMT in pan-cancer, it would be highly appropriate to further explore the relationship between TME and NNMT expressions in different types of cancers." (PMID 36817086, 2023). "Previous work has reported that NNMT is a central, metabolic regulator of CAF differentiation, and cancer progression in the stroma and inhibition of NNMT activity led to a reversion of the CAF phenotype." (PMID 36817086, 2023). "Here, we found that NNMT expression presents a significantly positive correlation with both stromal and immune components of TME in pan-cancer." (PMID 36817086, 2023). "NNMT, LDHB, and PTBP1 have been studied for promoting cancer development, but their synergistic effects with vemurafenib are not clear." (PMID 36829149, 2023). "Therefore, our study showed that high NNMT expression might predict the worse prognosis of cancer patients, and NNMT expression had the potential capacity to serve as a prognostic factor in various cancers, especially gastrointestinal cancer." (PMID 35233465, 2022). "OXPHOS inhibition‐sensitive cancer cells possess increased OXPHOS activity and silenced nicotinamide N‐methyltransferase (NNMT) expression." (PMID 36382559, 2022). "Our research revealed that NNMT expression is related to MSI in seven cancer types and TMB in fourteen cancer types." (PMID 36386816, 2022). "NNMT protein staining was relatively high in GBM, PAAD, STAD, COAD and KIRC cancer tissues compared with brain, pancreas, stomach, rectum and kidney normal tissues respectively." (PMID 36386816, 2022). "By altering epigenetic alterations and acting in several signaling pathways, NNMT-mediated depletion of NAM and S-adenosyl methionine (SAM) leads to metabolic and epigenetic reprogramming in cancers." (PMID 36386816, 2022). "We recently reported that the reduction of lipids in HBLs is positively correlated with nicotinamide N-methyltransferase (NNMT) downregulation, proposing that these cancer cells are consuming triglycerides as their requirement for energy in tumorigenesis." (PMID 36551847, 2022). "All these data thus suggest that SAM‐regulating protein NNMT and SAM‐consuming enzymes DNMTs function together in maintaining a cancer cell state, which is sensitive to OXPHOS inhibition." (PMID 36382559, 2022). "NNMT‐DNMT1 axis plays an essential role in maintaining cancer cell sensitivity to OXPHOS inhibition, and the statuses of NNMT and DNMT1 genes are faithful biomarkers for OXPHOS‐targeting cancer therapies." (PMID 36382559, 2022). "Although several studies described NNMT upregulation in RCC, the molecular events leading to enzyme overexpression, as well as the effect induced by such dysregulation in cancer cell phenotype, remain partly understood." (PMID 34439880, 2021). "Except IDO and TDO various enzymes of the kynurenine pathway have been identified as potential targets in cancer treatment such as nicotinamide phosphoribosyltransferase (NMPRT), nicotinamide N-methyltransferase (NNMT) and poly-(ADP-ribose) polymerase (PARP)." (PMID 34356899, 2021).
cancer (continued). "NNMT, the key metabolic enzyme regulating the differentiation of CAF and cancer progression, is a potential therapeutic target for HGSC metastasis." (PMID 34063807, 2021). "Nicotinamide N-methyltransferase (NNMT), which methylates nicotinamide using SAM, is overexpressed in a variety of cancers including lung, liver, kidney, bladder, and colon." (PMID 34109280, 2021). "NNMT indirectly, through depleting SAM, impairs methylation of histones and other proteins in cancer cells." (PMID 34073600, 2021). "Moreover, the NNMT expression affects cellular resistance to radiation-induced damage and the tumoral sensitivity to anti-tumor agents, suggesting that it could play a pivotal role in cancer cell metabolism." (PMID 34827592, 2021). "The connection between nutrient status, NNMT expression and its role in EMT should be considered with respect to cancer therapy." (PMID 33182817, 2020). "NNMT mediates SAM depletion and attenuating histone methylation in various cells, including cancer cells, which resulted in the extensive gene expression changes in the tumor stroma." (PMID 31989785, 2020). "Previous studies have reported that NNMT and/or its product, 1-MNA, are elevated not only in cancer but also in several metabolic syndromes." (PMID 36703437, 2020). "Nicotinamide N-methyltransferase (NNMT) is overexpressed in various human tumors and involved in the development and progression of several carcinomas." (PMID 31101119, 2019). "In the MD Anderson cohort 29% of luminal cancers showed overexpression of AURKA and downregulation of NNMT." (PMID 28102366, 2017). "Nicotinamide N-methyltransferase (NNMT), which converts nicotinamide to 1-methylnicotinamide (1-MNA), is overexpressed in a variety of human cancers and serves as a potential anti-cancer target." (PMID 27323852, 2016). "Identifying lesions at high risk of progression remains a critical goal, and, in the future, enzymes such as NNMT and PON2 may also serve as potential targets for molecular-based cancer therapies." (PMID 40941017, 2025). "However, due to the pivotal role played by NNMT in the deleterious behavior of cancer cells, targeting NNMT might represent an interesting strategy for counteracting tumor growth and chemoresistance, thus providing a rationale for novel anti-cancer therapies based on the inhibition of NNMT." (PMID 41301471, 2025). "Although further experiments are necessary to understand the specific mechanisms by which NNMT could participate to MCC tumorigenesis, our results seem to indicate that this enzyme may provide an interesting molecular target for cancer therapy." (PMID 38504052, 2024). "Taken together, these results suggest that NNMT could represent an interesting MCC biomarker and a promising target for targeted anti-cancer therapy." (PMID 38504052, 2024). "GLYR1 activity was elevated in RB1 mutant cancers and taking GLYR1 activity into account abolished the negative statistical relationship between RB1 mutation and NNMT expression." (PMID 37883365, 2023). "Rb-mutant cancers show increased total HMT activity and down-regulation of NNMT." (PMID 37883365, 2023). "Despite this considerable literature describing the roles of NNMT in cancer and lipogenesis in non-cancer diseases, there is a surprising lack of studies on possible links between NNMT and lipogenesis in cancer." (PMID 36750850, 2023). "NNMT is upregulated in cutaneous squamous cell carcinoma, induces cellular invasion via EMT-related gene expression and plays critical roles in the incidence and development of various cancers." (PMID 36902166, 2023). "However, our results also show that NNMT inhibition and DNMT1 overexpression cannot render OXPHOS‐resistant cancer cells sensitive." (PMID 36382559, 2022). "It thus appeared that, in a cancer-free condition, the contribution of NNMT in regulating NAM, SAM, SAH, and NAD is not prominent." (PMID 35705545, 2022).
cancer (continued). "After a systematic analysis of OXPHOS sensitive and resistant cancer cell lines, we revealed that SAM‐regulated enzyme NNMT and SAM‐consuming DNA methyltransferase DNMT1 negatively and positively correlated with cancer cell sensitivity to OXPHOS inhibition, respectively." (PMID 36382559, 2022). "Furthermore, recent evidence demonstrated that stromal nicotinamide N-methyltransferase (NNMT), an enzyme that impairs NAD+ biosynthesis by depleting its precursor N-nicotinamide, induces CAF differentiation and cancer progression." (PMID 35545049, 2022). "The expression of NNMT in OXPHOS sensitive (WSU‐DLCL2, NCI‐H82, and G‐401), moderately sensitive (Daoy, U‐87MG, and U251MG), and resistant (786‐O, CFPAC‐1, and SF126) cancer cells was experimentally verified, which shows undetectable NNMT expression in OXPHOS sensitive cancer cells." (PMID 36382559, 2022). "Moreover, we also used the TCGA data to validate our findings, and results also showed that high NNMT expression was an unfavorable factor of OS and DFS in human cancers, especially gastrointestinal cancers." (PMID 35233465, 2022). "Analysis of these tissues showed that NNMT protein expression varied within metastases from the same patient, independent of metastasis location or time after initial cancer diagnosis." (PMID 35678045, 2022). "Importantly, overexpression of NNMT reduces SAM and global methylation levels but increases SAH concentration in cancer cells sensitive to OXPHOS inhibition, while knockdown of NNMT in cancer cells resistant to OXPHOS inhibition increases SAM." (PMID 36382559, 2022). "NNMT can regulate NAD+ Metabolism and disrupt methyl donor balance in cancer cells." (PMID 35756670, 2022). "Generally, there was no increase in NNMT protein expression in metastases diagnosed at later versus earlier time points after the initial cancer diagnosis." (PMID 35678045, 2022). "Thus, the status of NNMT and DNMT1 in cancer cells provides an excellent base for developing biomarkers for selecting cancer patients suitable for therapies targeting the mitochondrial OXPHOS pathway." (PMID 36382559, 2022). "NNMT overexpression and DNMT1 inhibition render OXPHOS inhibition‐sensitive cancer cells resistant." (PMID 36382559, 2022). "NNMT overexpression and DNMT1 downregulation exhibit additive effects on reducing cancer cell sensitivity to OXPHOS inhibition, suggesting these proteins function together in maintaining a cancer cell state, which is sensitive to OXPHOS inhibition." (PMID 36382559, 2022). "Expression of NNMT remains low in tumor xenografts driven by OXPHOS inhibition‐sensitive cancer cell lines (NCI‐H82 and MDA‐MB‐453) compared with those driven by the resistant cancer cells (CFPAC‐1 and NCI‐H82‐OE‐NNMT/sh‐DNMT1), while the opposite expression pattern is observed for DNMT1." (PMID 36382559, 2022). "Further, the enhanced NNMT activity and increased NNMT reaction products due to the conversion to nicotinamide from NAM, NR, or NMN supplementation might potentially be related to cancer development." (PMID 36139711, 2022). "High levels of NNMT mRNA and high NNMT catalytic activity were detected in all of the papillary cancer cell lines, especially in BHP 2-7, BHP 7-13, BHP 10-3, BHP 18-21, and TPC1, compared to other cancer cell types and thyroid primary cells." (PMID 34827592, 2021). "What is key about this pathway is that it does not use SAM, thus one of the major routes by which NNMT influences the cancer phenotype—epigenetic regulation via reduced DNA methylation—is absent." (PMID 34680055, 2021). "Due to the discovery of a strong correlation between expression levels of NNMT and matrix metalloproteinase-2 (MMP-2), that is suggested to play an important role in cancer cell invasion, further analyses were carried out to disclose the interplay between both determinants of cellular invasiveness." (PMID 34439880, 2021).
cancer (continued). "NNMT has been shown to modulate the epigenetic environment in the differentiation process of stem cells and is elevated in cancer stem cells compared to non-tumour cells." (PMID 34680055, 2021). "NNMT protein levels were also elevated in metastatic and recurrent tumors compared to matched primary carcinomas, while normal ovary and fallopian tube tissue had no detectable NNMT expression." (PMID 28412735, 2017). "Interestingly, NNMT and other components of NAD(H) pathways are markedly induced in a variety of currently common cancers as well as in the metabolic syndrome, obesity, PD and autism." (PMID 22536229, 2012). "Inhibition of NNMT leads to a methyl overflow, which enhances trimethylation of histone H3K9 and increases DNA methylation at the promoters of PRDM5 and extracellular matrix-related genes in cancer cells, therefore being regarded as a promising anti-cancer target." (PMID 40529507, 2025). "Several NNMT inhibitors have been developed and show substantial potential as therapeutic strategies to address chemoresistance; however, to date, none have been approved for cancer treatment by the FDA." (PMID 40650308, 2025). "Moreover, considering the potential interplay between NNMT and other molecular pathways involved in cancer progression, such as the PI3K/Akt and Wnt/β-catenin pathways, will be essential for understanding NNMT-mediated oncogenesis and developing potential combinatorial therapeutic strategies." (PMID 38809277, 2024). "The expression of NNMT was closely related to the expression of many common immune checkpoints such as PD-L1 and CTLA-4, suggesting that NNMT may be involved in regulating the expression of immune checkpoint genes in cancer." (PMID 38809277, 2024). "NNMT could modify the SAM:SAH ratio affecting the methylation state of cancer cells, but also store N1-methylnicotinamide into tumor cells, thus fine-tuning the methylation state of cancer cells." (PMID 38504052, 2024). "However, a comprehensive pan-cancer analysis, integrating genomic datasets to systematically investigate NNMT dysregulation and its functional implications across various cancers, is currently lacking." (PMID 38809277, 2024). "In addition, in cancers which NNMT expression levels were correlated with poor prognosis, such as COAD, HNSC, OV, and STAD, macrophage levels were significantly upregulated in the NNMT high expression group." (PMID 36817086, 2023). "Although NNMT may exert a primary role in the first step of carcinogenesis by irreversibly methylating NAM, thus generating MNA, the effective role of this enzyme as well as NAD+ boosters on cancer development still need to be fully elucidated." (PMID 36139711, 2022). "However, the exact oncogenic role of NNMT in ccRCC as well as its metabolic functions in cancer cells have not been determined." (PMID 35440542, 2022). "We found that NNMT protein is weakly expressed in normal stromal cells of the lamina propria of benign colonic mucosa and can be significantly overexpressed in colorectal cancer tumor stromal cells but not in cancer cells." (PMID 35177765, 2022). "Additionally, overexpression of NNMT increased the levels of sirtuin 1 (SIRT1) in prostate and breast cancer cells, eventually promoting cell migration, invasion, and enhancing chemoresistance of cancer cells." (PMID 35338115, 2022). "Additionally, by their very selectivity, off-target effects can be minimised using inhibitors of NNMT activity rather than NNMT expression, making cancer therapeutics much more effective and tolerable for the patient." (PMID 34680055, 2021). "Although unlikely to lead to a cure for cancer when used alone, it is likely that when used as an adjunct therapy NNMT inhibitors will significantly improve the efficacy of other treatments as well as reduce the possibility for the development of drug resistance." (PMID 34680055, 2021). "However, there is no direct evidence showing increased NNMT activity upon exogenous SAM treatment to treat cancer." (PMID 33921923, 2021).
cancer (continued). "Among the candidate RCC tumor markers, NNMT, LCP1, and NM23A showed the highest features insignificance of difference in patients, the highest specificity in RCC compared to healthy individuals and several other cancers, and the best performances in the combination assay." (PMID 32992891, 2020). "Although recent studies have showed that NNMT expression played an important role in the tumor progression and might induce an unfavorable survival outcome for cancer patients, definite conclusion has not been obtained for small sample size and contradictory results of existing evidence." (PMID 35233465, 2022). "However, its biological effects have not been completely disclosed and the role of NNMT in cancer cell metabolism remains unclear." (PMID 34827592, 2021). "Therefore, it has been hypothesised that NNMT overexpression and subsequent reduction of intracellular nicotinamide in cancer stem cells removes PARP inhibition, conferring improved survival characteristics of cancer stem cells against DNA damage and programmed cell death." (PMID 35205743, 2022). "NNMT should thus be regarded not as a solitary oncogenic effector but as a pivotal metabolic checkpoint that indirectly regulates SIRT1 activity, positioning it at the intersection of NAD+ and SAM metabolism in cancer." (PMID 41008982, 2025). "Considering that NNMT upregulation in the liver does not decrease NAD+ level, in contrast to adipose tissue, concomitant stabilization of SIRT1 by NNMT and the ability of liver to synthesize NAD+ de novo from Trp may allow for SIRT1 overactivation in this type of cancer." (PMID 34073600, 2021).